GCG (glucagon)
Diseases named in the same sentence as GCG in open-access papers (continued):
Sharing a sentence is not in itself a finding about the gene and the disease.
metabolic syndrome (continued). "Importantly, the inverse relationship remains significant after adjustment for several confounders potentially affecting either circulating IGF-1 or fasting glucagon levels, including age, gender, adiposity, insulin sensitivity, dyslipidemia and glucose tolerance status." (PMID 28881681, 2017). "Accordingly, our aim was to investigate the relationship between the glucagon to insulin ratio and metabolic syndrome in T2DM patients, in order to identify the effect of glucagon on cardiovascular disease." (PMID 37762748, 2023). "While the mechanism could involve stimulation of ACTH or glucagon, in the reported study, the primary finding was that V1b receptor amplified fructokinase expression, an effect that can enhance the production of fat and other features of the metabolic syndrome." (PMID 34199607, 2021). "We propose that this insulin/glucagon synergism plays a role in mediating the elevation in FGF21 production during starvation and conditions related to metabolic syndrome." (PMID 24733293, 2014). "Subjects with features of metabolic syndrome had higher levels of C-peptide, GIP, insulin, leptin, PAI-1, and lower levels of ghrelin, whereas overweight and obese individuals had increased levels of GIP, leptin, glucagon, and decreased levels of ghrelin." (PMID 35409072, 2022). "However, the molecular mechanisms that influence the lipid profile in the non-fasting state are quite different between age, as well as the possible intervention of glucagon and FGF21 in the control of dyslipidemia." (PMID 31405194, 2019). "Increased glucagon can result in hepatic gluconeogenesis contributing to metabolic syndrome cancer cachexia leading to negative energy balance, weight loss and reduced food intake." (PMID 31889941, 2019). "Finally, glucagon or GLP-1 receptor agonists have been combined with hormone nuclear receptor agonists for estrogens, androgens, and thyroid hormones, as the activation of their nuclear receptors is known to induce beneficial effects for metabolic syndrome." (PMID 31337027, 2019).
Glucose intolerance (66 papers, 2007 to 2025). Glucose intolerance (GI) can be defined as dysglycemia that comprises both prediabetes and diabetes. "N-Acetyl Cysteine rescues glucose intolerance, glutamate accumulation and glucagon production in the pancreatic islets of ATM-deficient mice." (PMID 39281865, 2024). "Interestingly, enhanced insulinemia and glucose intolerance of tau KI mice under HFD were associated with an increased fraction of β-cell in the islets of tau KI mice as compared to WT littermates while glucagon-producing α-cells remained unaffected." (PMID 35250480, 2022). "A previous study reported reduced glucagon suppression in individuals with CF and glucose intolerance during an oral glucose tolerance test (OGTT), suggesting that functions of other islet cell types are also affected by the CFRD pathology." (PMID 37720541, 2023). "By using it, it was substantiated that the GLP-1RA liraglutide was effective in preventing the development of glucose intolerance, improving insulin and glucagon secretion control, and reducing ER stress in Langerhans islets in Wfs1−/− rats." (PMID 37333802, 2023). "Alpha cell–specific IRS1-knockout mice exhibited glucose intolerance and inappropriate glucagon suppression during glucose tolerance tests." (PMID 33839150, 2021). "Chronic GCGR agonism induces glucose intolerance, fitting this classical view; however, the role of glucagon in glucose metabolism is expanding." (PMID 33411693, 2021). "At 0.4 mg/kg, DE-71 produced a less pronounced glucose intolerance and an apparent reduction in insulin and reduced glucagon." (PMID 33093533, 2020). "As was the case in younger mice, adult αGckKO female mice had a higher fed plasma glucagon level (+45%) than Ctrl mice, and developed mild glucose intolerance after an overnight fast." (PMID 29416045, 2018). "As mice fed KD for 6 days already exhibited impaired insulin sensitivity, resulting in glucose intolerance, we examined blood glucose, insulin, and glucagon levels in wild-type and Fgf21 knockout mice fed NC or KD for 6 days." (PMID 23874946, 2013). "Environmental stress plays an important role in the development of glucose intolerance influencing lipid and glucose metabolism through sympathetic nervous system, cytokines and hormones such as glucocorticoids, catecholamines and glucagon." (PMID 21569357, 2011). "This study may not have detected functional impairments in the early stages of glucose intolerance, which needs to be evaluated and validated using oral glucose and glucagon tolerance tests." (PMID 39145114, 2024). "A subset of α cells in culture showed GLP-1R expression and α-cell specific GLP-1R knockout (KO) mice exhibit mild glucose intolerance and increased glucagon secretion in response to glucose challenging compared with wild-type animals, suggesting a possible direct effect of GLP-1 on this cell." (PMID 37729025, 2023). "Using a model of inducible hyperglucagonemia caused by mTORC1 activation in α cells, our studies uncovered a potentially novel biphasic response characterized by an early phase of glucose intolerance followed by a phase of reduction in liver glucagon action and restoration of glucose tolerance." (PMID 37140984, 2023). "They provide a basis for determining whether glucagon-regulated gluconeogenesis is one of the reasons for glucose intolerance in carnivorous fish and further finding targets to improve this disorder." (PMID 37048171, 2023). "Abnormal glucagon secretion that has been shown to contribute to the development of glucose intolerance may contribute to the functional differences in our 5HT-sublines." (PMID 36768493, 2023). "In 0.4 mg/kg F1 insulin reduction was less pronounced, and glucagon was decreased, which could explain the less marked glucose intolerance." (PMID 33093533, 2020).
Glucose intolerance (continued). "Early chronic intervention with the GLP-1 receptor agonist liraglutide starting before the onset of metabolic symptoms prevented the development of glucose intolerance, improved insulin and glucagon secretion control, reduced ER stress and inflammation in Langerhans islets in Wfs1 mutant rats." (PMID 29976929, 2018). "Increases in the levels of alanine, a highly gluconeogenic amino acid responsible for glucagon to regulate gluconeogenesis, could contribute to the development of glucose intolerance in LD." (PMID 30577665, 2018). "Although the mechanism is unclear, enhanced glucagon secretion may deteriorate the glucose intolerance in TG mice." (PMID 22384192, 2012). "Adult male α-cell specific Insr knockout (αIRKO) mice have been shown to exhibit mild glucose intolerance, hyperglycemic and hyperglucagonemia in the fed state and enhanced glucagon secretion in response to L-arginine stimulation which led to increased glucose release from the liver." (PMID 22479612, 2012). "Therefore, glucagon-regulated gluconeogenesis may be responsible for glucose intolerance in carnivorous fish." (PMID 37048171, 2023). "In this view, the increased GIP levels deserve attention too, as they are able to stimulate glucagon secretion; such effect may help to stabilize glucose levels in healthy individuals, whilst in T2D and obese subjects these may contribute to glucose intolerance." (PMID 30451975, 2019). "To address if glucose intolerance and impaired insulin secretion in female Adrb2 cKO mice stemmed from defective islet formation and/or maintenance, we performed immunostaining for the islet hormone markers, insulin and glucagon, in adult animals at 2 months of age." (PMID 30303066, 2018). "This hypothesis is supported by a recent study where low circulating glucagon levels accompanied with low 7B2 mRNA and protein levels (but not PC2 levels) were reported in pancreas of a mouse strain highly predisposed to age associated glucose intolerance." (PMID 17617923, 2007). "Moreover, glucagon secretion was negatively associated with insulin in the late phase of the OGTT, which might explain the delayed suppression of glucagon in those with glucose intolerance." (PMID 37720541, 2023). "In vivo zebrafish and mouse models exhibited glucose intolerance, decreased peak GSIS, decreased expression of β-cell identity markers, increased insulin and glucagon co-staining cells, and reduced Tgfb2 and Smad2 expression." (PMID 34246804, 2021). "The lack of glucose intolerance after chronic elevation of glucagon in αRhebTg mice and the reduced responses to glucagon administration recapitulate the glucagon resistance phenotype observed in mice with constitutive hyperglucagonemia by constitutive deletion of TSC2 in α cells." (PMID 37140984, 2023).
short bowel syndrome (59 papers, 2009 to 2026). "When monitoring changes in nutrient absorption, we measured blood glucose, insulin, glucagon, and amylin levels in patients with short bowel syndrome during a meal test." (PMID 40886373, 2025). "As such, intramuscular glucagon is well established in rescue of hypoglycaemia, while GLP-2 analogues are indicated in the management of short bowel syndrome." (PMID 34093449, 2021).
insulinoma (57 papers, 1986 to 2025). "Historically, several other diagnostic tests have been used in the diagnostic work-ups of canine insulinoma patients, including the amended insulin-to-glucose ratio, the intravenous glucose tolerance test and the glucagon tolerance test." (PMID 36288153, 2022). "In MEN1 patients, it has also been shown that early onset pancreatic microadenomas with loss of heterozygosity (LOH) of MEN1 express glucagon, whereas more advanced hormone-secreting tumours in the same patients were predominantly insulinomas." (PMID 32348957, 2020). "New agents under investigation as treatment options for malignant insulinomas associated with refractory hypoglycemia include anti-insulin receptor monoclonal antibodies, oral somatostatin receptor drugs, and soluble stable glucagon." (PMID 36494838, 2022). "When hypoglycemia is insulin mediated due to an insulinoma, then glucose levels are expected to rise greater than 25 mg/dL (1.39 mmol/L) within 15 minutes following the glucagon challenge." (PMID 40083398, 2025). "SSA can paradoxically worsen or unmask hypoglycaemia in patients with insulinoma by inhibiting counter-regulatory hormones such as glucagon and growth hormone." (PMID 40697399, 2025). "Insulinoma 2 showed both insulin and glucagon staining in the insulinoma tissue and INS-DRiP colocalized with insulin+ cells and glucagon+ cells, and triple positive cells." (PMID 38596681, 2024). "On the contrary, these control cells expressed a high level of glucagon with ~70% positively stained, suggesting a possible impaired glucose tolerance in untreated insulinoma cells." (PMID 37195917, 2023). "The HK1 expression in clusters cultured in stromal medium that was about double that of those in differentiation medium as well as the presence of glucagon in clusters substantiates, at minimum, a lower potential for insulinoma formation." (PMID 35769100, 2022). "In other mouse models of PanNETs21,24,25, MEN1 deletion using the insulin or PDX1 promoter driven Cre construct, insulinomas, glucagon-expressing tumors and well differentiated PanNETs were also observed." (PMID 30315258, 2018). "Tumor 9, which came from a patient with a clinical diagnosis of insulinoma had a high level of glucagon expression; the clinical diagnosis was apparently due to the other tumor (#8) which did have a high level of insulin expression." (PMID 15691381, 2005). "The immunoreactive glucagon and somatostatin contents of extrapancreatic tissues of insulinoma-bearing rats were unchanged." (PMID 2877684, 1986). "The lack of increase in plasma glucose following glucagon was not consistent with the expected response seen in conditions associated with high insulin states such as insulinoma." (PMID 40083398, 2025). "Blunted post-glucagon increase in glucose levels is inconsistent with insulinoma and may serve as another clue, indicating that other acute etiologies should be investigated." (PMID 40083398, 2025). "Positive or scattered glucagon expression was seen in about 60% of insulinomas." (PMID 32103422, 2020). "The LC/MS data obtained from the two glucagonoma cases (Case 1 pre‐ and post‐treatment, and Case 2), an insulinoma (Case 3) and 62 control samples from healthy individuals were interrogated for glucagon, CHGA, CHGB, SCG2, insulin, c‐peptide, and the internal standard bovine insulin." (PMID 29857350, 2018). "Insulinoma (70%) and gastrinoma (20%) are the most frequent functional pNENs, while the remaining so-called rare pNENs include various hormones (5%–10%), such a vasoactive polypeptides (vipoma), glucagon (glucagonoma), serotonin, renin, and GLP1 (glucagon-like peptide 1)." (PMID 37771441, 2023). "Additionally, although InR1G9 cells secrete glucagon, they are derived from insulinoma." (PMID 35409362, 2022).
insulinoma (continued). "In normal mouse pancreatic islets, α-cells are located on the periphery of the islet secrete glucagon, whereas β-cells are located at the centre of the islet secrete insulin, and hence, it would be expected that glucagonomas would arise from α-cells and insulinomas from β-cells." (PMID 32348957, 2020). "Moreover, overexpression of Pdx1 eliminated glucagon mRNA and protein and promoted the expression of β-cell specific genes, while induction of dominant-negative Pdx1 resulted in differentiation of β-cells into α-cells in the rat insulinoma cell line." (PMID 26845333, 2016). "We investigated the effect of adropin on insulin and glucagon secretion using pancreatic tissue fragments of normal and diabetic rats and the INS-1 832/3 rat insulinoma cell line." (PMID 39337311, 2024). "Pancreas sections derived from Whipple procedures of two insulinoma patients were stained for INS-DRiP, insulin, and glucagon." (PMID 38596681, 2024). "After insulinoma excision, patients can have elevated BSL due to suppression, atrophy, and degranulation of the remaining beta-pancreatic cells, effects of glucagon, glucocorticoids, and growth hormone in the immediate postoperative period." (PMID 38883112, 2024). "In functional tumors, measurement of specific hormones is appropriate [glucagon in glucagonoma, vasoactive intestinal peptide (VIP) in VIPoma, gastrin in gastrinoma, insulin in insulinoma, etc.]." (PMID 36950054, 2023). "Here, along similar GCG-INS axes, we have shown the insulin-expressing cells from the canine insulinoma samples examined show strong expression of INS and no expression of GCG, consistent with their clinical classification as insulinomas." (PMID 40438247, 2025). "Following 1 mg glucagon injection, the patient's glucose did not improve, a response inconsistent with insulinoma." (PMID 40083398, 2025). "In contrast to normal feline β cells, insulinoma cells express the HK1 gene and do not show glucagon protein expression, similar to lacking glucagon protein expression within Men1-ablated murine insulinomas." (PMID 35769100, 2022). "The process of tumour detection involved biochemical screening tests including gastrin, glucose, insulin, chromogranin-A, pancreatic polypeptide, glucagon, vasointestinal polypeptide, prolactin and IGF-1 to assess for gastrinoma, insulinoma, enteropancreatic and anterior pituitary tumours." (PMID 31797261, 2020). "Consistent with previous reports, miR-204 expression was enriched in insulinomas and drastically lower in both non-functional PETs and functional PETs expressing glucagon or somatostatin." (PMID 29070792, 2017). "While Grb10 knock-down in the rat insulinoma cell line INS-1 lacking glucagon resulted in marked reduction of insulin, GRB10 knock-down in human pancreatic islets resulted in reduction in both insulin and glucagon secretion and expression." (PMID 24699409, 2014). "The expression of ATP6AP2 proteins was clearly detected in insulin-expressing cells of normal islets near the insulinoma lesions and nonfunctioning NETs, whereas it was not or faintly detected in glucagon-expressing cells and somatostatin-expressing cells in the same regions." (PMID 37286698, 2023). "Finally, it remains to be determined, if the spectrum of the human MEN1-syndrome can be fully recapitulated in mice, since glucagon cell specific deletion of MEN1 in mice resulted in the development of insulinomas and not glucagon producing cells." (PMID 27769070, 2016). "Insulin, glucagon, ARID1A, H3K36me3 IHC, and CDKN2A FISH were only tested on 31 cases, as for the last four insulinoma cases, no unstained TMA slides were available." (PMID 32103422, 2020).